IL1B (interleukin 1 beta)
Diseases named in the same sentence as IL1B in open-access papers (continued):
Sharing a sentence is not in itself a finding about the gene and the disease.
cancer (continued). "TNF-α and IL-1β, cytokines with a pivotal action in both local and systemic inflammation, are of great importance in cancer development as it is involved in the regulation of cell proliferation and apoptosis." (PMID 37772231, 2023). "Due to the relationship between chronic inflammatory states and cancer, serum levels of IL-1β, IL-6, IL-8 have been studied as potential biomarkers of malignancy." (PMID 37511306, 2023). "Reduced inflammasome and IL-1β expression prevented cancer cell development, according to melanoma studies." (PMID 37715239, 2023). "Secreted inflammatory cytokines in cancer cells, including IL-22, IL-6, IL-8, IL-4, IL-1β, HGF, IGF-1, EGF, G-CSF, TNF-α, VEGF, and IL-11, can confer the promotion of chemo- and radioresistance." (PMID 38140352, 2023). "In the rat glia cell line C6, LRRC15 is mildly regulated in response to proinflammatory cytokines like IL1β, IL6, and TNFɑ, and more recently TGFβ signaling has been linked to LRRC15 expression in cancer-associated fibroblasts." (PMID 36757924, 2023). "The MAPK and NF-κB signaling pathways activate IL-1β–induced cancer cell migration and invasion, and inhibition of IL-1β–induced migration and invasion by an inhibitor or RNAi reduces cancer cell migration and invasion." (PMID 38188678, 2023). "The release of lactate dehydrogenase (LDH) and IL-1β into the supernatant of cancer cells following stimulation was increased with IL-17A treatment." (PMID 37211606, 2023). "After the cancer cells trick the astrocytes into overactivation, astrocytes enter a vicious cycle of continuous overactivation by IL1β and TGF-β2." (PMID 36835266, 2023). "Evidence from documented studies and in vivo experiments suggests the activation of inflammasomes and related cytokines, such as IL-1β, in many human cancers." (PMID 38026959, 2023). "The IL1B gene has been extensively investigated in relation to cancers and inflammatory and infectious diseases." (PMID 37147350, 2023). "T lymphocytes promote calreticulin exposure, HMGB1 and IL-1β release, leading to DC uptake and cross presentation, providing a mechanism for amplification and self-perpetuation of the immune response against cancer neoantigens." (PMID 38077402, 2023). "In detail, activated transcription factors, such as FOXO1, HIF1A, STAT3, and JUN, regulate the expression of TGFB1, TGFB3, IL1B, and TNF, promoting cancer hallmarks associated with these ligands." (PMID 37370765, 2023). "Our results show that TonEBP plays an important role in IL-1β–induced cancer cell migration and invasion and that some of these effects proceed via the regulation of PAK1 expression in A549 cancer cells." (PMID 38188678, 2023). "IL-1β is a key mediator of the inflammatory response and is involved in diverse physiological and pathological processes, including inflammation, cancer, and immunity." (PMID 37208690, 2023). "Nevertheless, it is essential to acknowledge the context-dependent and sometimes contrasting effects of the NLRP3 inflammasome and its product, IL-1β, on tumorigenesis depending on various cancer cell types." (PMID 38026959, 2023). "Many research works focus on the relationship between cancer metastasis and inflammasome activation in myeloid cells, because IL-1β in TME is predominantly produced by myeloid cells." (PMID 36932407, 2023). "Targeting IL-1β, therefore, has the potential to enhance the effectiveness of ICIs and other cancer treatments." (PMID 37511306, 2023). "As a vital pro-inflammatory cytokine, IL-1β promotes cancer development via many different manners in the primary tumor." (PMID 37443052, 2023).
cancer (continued). "It is clear that IL-1β has a wide range of effects in different cancers and cardiometabolic diseases as well, thus future treatments with IL-1β blockers should take into consideration the aformentioned adverse possibilities." (PMID 36611037, 2023). "The clinical strategy to take advantage of anti-IL-1β blockade in cancers has thus remained undetermined." (PMID 37441079, 2023). "The literature indicates that IL-1β contributes significantly to cancer-promoting inflammation in a wide variaty of cancers." (PMID 36611037, 2023). "Inhibition of IL-1β signaling in malignant tumors are now considered as potential targets for cancer therapy." (PMID 36835413, 2023). "NLRP3 can be activated through cross-talk between TAMs and cancer cells leading to promoted migration of cancer cells in IL-1β dependent manner." (PMID 36932407, 2023). "This indicates that IL-1β induces cancer cell migration and invasion via the ERK and NF-κB signaling pathways." (PMID 38188678, 2023). "Increasing with cancer progression, the concentration of MGAs positively correlated with the secretion of ILs: IL-1β, IL-2, IL-4 and IL-6." (PMID 37970208, 2023). "The cytokines interleukin‐1 alpha (IL‐1α) and interleukin‐1 beta (IL‐1β) have also been investigated as anti‐cancer agents in preclinical and clinical studies." (PMID 37206237, 2023). "M1 macrophages can produce reactive oxygen species (ROS) and inflammatory cytokines, such as tumor necrosis factor-alpha (TNF-α) and interleukin-1 beta (IL-1β), which contribute to metabolic alterations and cancer-related inflammation." (PMID 37492564, 2023). "In summary, this study shows that macrophage AIM2 is activated by nucleic acids secreted from the cancer cells, which leads to inflammasome activation, IL-1β cleavage and release from macrophages." (PMID 37449203, 2023). "Many cancer-related cytokines, such as IL-1β, IL-6, and TNF-α, are elevated during oral infections due to LPS stimulation." (PMID 37249977, 2023). "Gene expression of cancer-associated adipocyte pro-inflammatory markers CXCL8, CCL2 and IL-1β was increased in hADMSC treated with EVs." (PMID 37833751, 2023). "Not only enhancing cancer cell proliferation, upregulated IL-1β expression results in an immunosuppressive TME, promotes the EMT of malignant cells, invasion, and the subsequent metastasis." (PMID 37444617, 2023). "Our observations have suggested that MDSC secreted IL-10/IL-6/IL-1β are the critical players modulating the drug resistance of cancer cells via STAT3/STAT1/NF-κB pathway." (PMID 38304256, 2023). "IL-1β, on the other hand, has been shown to play a role in the development of the premetastatic niche, and targeting the inflammasome-IL-1β pathway has been proposed as a novel approach for cancer treatment." (PMID 37715239, 2023). "This indicates that normal cells can respond to cytokine stimuli to induce IDO1, but the IL-1β-mediated induction of IDO1 was specific to cancer cells." (PMID 37985999, 2023). "PIGF signaling activates inflammatory cytokine releasing, such as IL-1β and IL-6, to promote angiogenesis in several types of cancer." (PMID 35895109, 2023). "A similar effect is seen with Il1β rs1143634, which is known for its activity in skin immunity, and was also found to be involved in cancer development, where it stimulates activated blood monocytes and tissue macrophages." (PMID 37763073, 2023). "As already described, TNFα and IL-1β are involved in various pathological processes, such as chronic inflammation, autoimmunity, and cancer, and both cytokines are highly relevant to the inflammatory condition of breast tumors." (PMID 37208442, 2023). "As the expression of cytokines such as IL-1B correlates with poor prognosis across different cancer types, more advanced cancer stage and metastatic spread, the importance of BNC2 regulating these matrisome-adjacent genes also warrants further investigation." (PMID 37536977, 2023).
cancer (continued). "For example, it is known that AIM2 can regulate PD-L1, and that IL-1β is able to increase PD-L1 at the membrane of cancer cells and CAFs." (PMID 37819510, 2023). "The Gasdermin (GSDM) family member genes NLRP3, NLRC4, NLRP1, AIM2, IL-1β, and IL-18 are linked to TIME, and the immunosuppressive microenvironment can be overcome by targeted pyroptosis therapy in cancers." (PMID 36882663, 2023). "When activated, the NLRP3 inflammasome stimulates the release of pro-inflammatory cytokines IL-1β and IL-18, which promote the progression of cancer." (PMID 37345134, 2023). "Interleukin 1 alpha (IL1A) and interleukin 1 beta (IL1B) belong to the IL-1 protein cluster and are involved in chronic inflammation, as well as in cancer development." (PMID 37189693, 2023). "There are data on the inhibition of the synthesis of TGFβ, TNFα, IL-6, and IL-1β by progestins in cancer cells." (PMID 37298830, 2023). "Exogenous IL-1β stimulated proliferation of TRAMPC2 cancer cells, and addition of exogenous IL-1β stimulated proliferation of TRAMPC2 cancer cells similarly in the presence of WT and AIM2-/- or Caspase1/11-/- macrophages." (PMID 37449203, 2023). "Increased production of pro-inflammatory cytokines such as IL-1β, IL-6, TNF-α and MCP-1 has also been linked to various types of cancer." (PMID 37173732, 2023). "Recombinant IL‐1 ligands (marketed as Dainippon/Immunex [IL‐1α] and Syntex [IL‐1β]) were administered to cancer patients with the most common symptoms being flu‐like symptoms including fever, chills, rigors and nausea." (PMID 37206237, 2023). "As IL-1β was discovered long before IL-18, its role in inflammation and cancer progression has been vastly studied and well-reviewed." (PMID 37298187, 2023). "The role of IL-1β in cancer is complex, and its ability to directly alter the TME has been studied in the preclinical setting." (PMID 37511306, 2023). "First, we tested the cytokine production (IL-1β, IL-6, and IFNα) of peripheral blood mononuclear cells (PBMCs) co-incubated with cancer cells by FACS analysis." (PMID 36831616, 2023). "Modulating the expression of TonEBP in A549 cells did not directly mediate IL-1β but altered the responsiveness of IL-1β to affect cancer cell migration and invasion." (PMID 38188678, 2023). "The opposite effect of P4 on cytokine production in cancerous and noncancerous cells has been demonstrated in studies: P4 mostly down-regulated IL-1β, IL-6, and TNFα in cancer cell lines and tissues." (PMID 37298830, 2023). "In conclusion, KRAS-mutant cancers rely on host IL-1β, which they elicit from host macrophages via secretory versican that activates myeloid IKKβ." (PMID 36980752, 2023). "IL-1β secreted from cancer cells can sufficiently regulate the pro-inflammatory phenotype of adipocytes via the upregulation of COX-2 and monocyte chemoattractant protein-1 (MCP1)." (PMID 36672449, 2023). "Based on previous research, it is known that the activation of NLRP3 inflammasome can promote cancer progression by releasing inflammatory cytokines such as IL-1β." (PMID 38026959, 2023). "Inflammasome's dual effects in cancer seem to be dependent on several factors, such as expression, the stage of tumorigenesis, cancer type, and the presence of mutations affecting PRR expression and downstream effector molecules (e.g., IL-1β/18)." (PMID 37564206, 2023). "Here, we show that human KRAS-mutant cancers are addicted to IL-1β via inflammatory versican signaling to macrophage inhibitor of NF-κB kinase (IKK) β." (PMID 36980752, 2023). "Conglomeration of all our observations has suggested that MDSC secreted IL-6/IL-10/IL-1β are the supreme players regulating the drug resistance of cancer cells via STAT1/STAT3/NF-κB pathway." (PMID 38304256, 2023). "The effector cytokines, IL-1β and IL-18, released during chronic inflammation, induce cancer cell proliferation in a paracrine and autocrine manner." (PMID 37891577, 2023).
cancer (continued). "Tumor necrosis factor (TNF)-α, IL-8, IL-1β, and vascular endothelial growth factor secretion by cancer cells was significantly increased by coculture of AGS cells with GC-derived CD19+ B cells." (PMID 37946227, 2023). "So, this finding confirms the role of MDSC secreted IL-1β mediated MDR in cancer cells by activating NF-κB signaling cascade." (PMID 38304256, 2023). "Inflammatory cytokines, such as IFN- γ, IL-1β, IL-2, IL-4, IL-6, IL-10, IL-12p70, and TNF-α, have been shown to be involved in the immune response associated with cancer progression." (PMID 37373987, 2023). "IL-1β, a potent and versatile cytokine released from TAMs, plays a pivotal role in cancer cell proliferation, neoplastic progression, and metastasis." (PMID 37444617, 2023). "Helicobacter is a known pathogen and has also been linked with the elevation of IL1-β, tumor necrosis factor (TNF)-α expression, and carcinoma." (PMID 37375003, 2023). "Collectively, this suggests a unique and significant role played by IL-17 and Th17 polarized cells in the development of esophageal squamous dysplasia/carcinoma in IL-1β transgenic mice." (PMID 37543673, 2023). "Inhibition of IL1β by Canakinumab has previously been shown to adversely affect immunity in cancer patients." (PMID 36230739, 2022). "Monoclonal antibodies can target immune checkpoints (e.g., PD-L1 and CTLA-4), tyrosine kinase and subsequent signaling pathways (e.g., VEGF), and cytokines in cancer patients (e.g. IL-6 and IL-1β)." (PMID 35054524, 2022). "One of the reasonable explanations is that IL-1β participates in the construction of an inflammatory tumor microenvironment, promoting carcinogenesis in several cancers." (PMID 36204568, 2022). "Anti-inflammation with canakinumab targeting IL-1β significantly reduces cancer occurrence and mortality." (PMID 35223517, 2022). "IL-1β is a common pro-inflammatory cytokine that can turn on immunosuppressive mechanisms and promote cancer development." (PMID 35645817, 2022). "On the other hand, anakinra (a selective antagonist of the IL-1 receptor, which inhibits both IL-1α and IL-1β) has shown a significant effect in reducing clinical symptoms in different cardiovascular diseases and cancer." (PMID 36611853, 2022). "Activated NF-κB in HCC cells has been found to promote the expressions of inflammatory cytokines (e.g., IL-6, IL-1β), which creates a cancer-promoting inflammatory microenvironment and is involved in the carcinogenesis and progression of HCC." (PMID 36260873, 2022). "Saliva cytokine levels of IL-1β, IL-2, IL-6 and TNF are not only associated with oral inflammation but also with the severity of oral mucosal damage in cancer patients." (PMID 35844493, 2022). "An inflammatory cytokine, IL-1β, influences immune cells, proliferation, migration, angiogenesis, and metastasis in cancer." (PMID 36430487, 2022). "Pyroptosis-based cells exhibited the activation of caspase-8/3, the release of inflammatory factors (IL-18, IL-1β, etc.)and a strong relationship to inflammation, immunity and cancer." (PMID 36501209, 2022). "In this review, we will discuss inflammaging in the elderly, specifically concentrating on IL-6 and IL-1b in the context of T lymphocytes, and how inflammation is related to mortality and morbidities, specifically cardiovascular disease and cancer." (PMID 35821823, 2022). "To further explore ingredients in the cancer culture medium and their mechanisms for the observed effects on cardiomyocytes, we examined the interleukin-1α (IL-1α), IL-1β, transforming growth factor-β (TGF-β) levels in medium by ELISA." (PMID 35265687, 2022). "In this work, the authors showed that IL-1β induced the epithelial-to-mesenchymal transition of cancer cells through the hypoxia-inducible factor 1α (HIF-1α), thereby initiating the metastatic process." (PMID 36551635, 2022).
cancer (continued). "An uncontrolled increase in IL-1β release exerts immune-suppressive effects and influences all the initiation-to-progression stages of many types of cancers and represents an emerging critical contributor to chemoresistance." (PMID 35530309, 2022). "Inflammatory agents, including IL-1β, IL-6, and IFN-γ, play a key role in DNA methylation, and thereby have a close association with cancer, and the JAK-STAT cascade is a bridge between inflammation and cancer." (PMID 35184640, 2022). "This is relevant to cancer immunotherapy, as several studies have proposed that acute IL-1β signaling is essential for antitumor immunity." (PMID 36127465, 2022). "IL-1β, IL-12, and IL-10 were all upregulated in the supernatants from the macrophage-with-cancer-cell groups compared with those from the control, cancer-cell, DLL3-overexpressed-cancer-cell, and macrophage groups." (PMID 35382168, 2022). "Consistently, androgen depletion or AR-pathway inhibitors (ARI) derepressed IL1β in AR-positive cancer cells, both in vitro and in vivo." (PMID 36561929, 2022). "Interleukin-1 (IL-1) is a proinflammatory cytokine with a high relevance in cancer; 11 ligands and receptors have been described in this family, where IL-1β has high relevance in the inflammation process." (PMID 35681719, 2022). "The pro-inflammatory factor IL-1β plays an important role in the development of many diseases, including cancer, so this study examined the effect of 5DN and its metabolites (M1, M2, and M3) on LPS-induced IL-1β production in RAW 264.7 cells." (PMID 36552328, 2022). "IL‐1β activates MDSCs in vitro and in vivo through an IL‐1RI/NF‐κB pathway, leading to cancer development." (PMID 35791509, 2022). "Cytokines like tumor necrosis factor-α (TNF-α) and IL-1β can also promote the proliferation of cancer cells." (PMID 35645817, 2022). "Despite the established role of inflammasome pathway in the orchestration of an inflammatory response, through release of pro-inflammatory cytokines IL-1β and IL-18, its role in cancer development, progression, and immunotherapy response remains contradictive." (PMID 36032139, 2022). "All plasma levels of neutrophil number, neutrophilic percentage, IL-1β, IL-8, and IL-6 in cancer patients with metastases were significantly higher than those without metastases (P < 0.05 for all)." (PMID 36157224, 2022). "When querying the Cancer Genome Atlas data set, we found positive correlations between IL1B expression and infiltration of immunosuppressive PMNs and expression of their chemoattractant, CXCL1, and PDCD1 expressions in patients with KM-LUAD." (PMID 35471938, 2022). "In general, cancer is a procoagulant state as it can activate the tissue factors and release inflammatory cytokines (i.e., TNF-α, IL-1β) which increases the risk of thrombosis and hence MI." (PMID 35228975, 2022). "MDSC levels in patients with active TB were comparable to those in patients with cancer and contributed to reduced Th1 cytokine expression, whereas proinflammatory cytokines, such as IL-1β, IL-6, IL-8, and monocyte chemoattractant protein-1, were increased." (PMID 35092727, 2022). "One of the key members of the IL family, IL-1β, has pleiotropic effects on immune cells, angiogenesis, cancer cell growth, migration, and metastasis." (PMID 36430487, 2022). "IL‐17 cytokines family can activate the production of NF‐κB, IL8, IL6, TNF‐α, and IL1b, contributing to various inflammatory diseases and cancers." (PMID 35373393, 2022). "The inflammatory cytokine IL-1β has been found to modulate the expression of various miRNAs linking inflammation to cancer progression." (PMID 35842651, 2022). "Neither the guidelines nor the ASCO education book discuss the role of inflammation and cytokines, such as IL-1β, IL-6, JAK/STAT pathway, or IFN-γ, all of which have been associated with cancer cachexia." (PMID 36358681, 2022).